TRAF3 (TNF receptor associated factor 3)
Diseases named in the same sentence as TRAF3 in open-access papers (continued):
Sharing a sentence is not in itself a finding about the gene and the disease.
cancer (continued). "We have recently reported that mCD40L differentially regulates TRAF adaptor protein expression in normal and malignant epithelial cells, with TRAF3 stabilisation being central in the induction of apoptosis in carcinoma cells." (PMID 36291141, 2022). "Among these mRNA targets, TRAF3, which is widely reported in assorted cancers, was selected through corroboration by qRT‐PCR and IHC in CRC tissues." (PMID 33784010, 2021). "TRAF2 and TRAF3 reveal both activities (i.e., cell death and survival) and thus finding gene alteration status in a specific cancer type is important for the understanding cancer-related functions of TRAF2 and TRAF3." (PMID 34257589, 2021). "Truncation and fusion of TRAF3 are less common but also detected in several different types of human cancers." (PMID 30294322, 2018). "Other negatively regulating proteins are XAF-1, which binds XIAP and was found to be downregulated in a majority of the NCI60 cancer cell line panel, and TRAF3, which promotes the degradation of the cIAP1/2-TRAF2-complex." (PMID 27167336, 2016). "HPV-related cancers were characterized by mutation of the PIK3CA gene, novel alterations involving loss of TRAF3 function, and amplification of the cell cycle gene E2F1." (PMID 27776338, 2016). "As predicted, these genetic alterations also differed from HPV-driven cancers involving the base of tongue, which had a higher frequency of activating mutations in PIK3CA, with loss of TRAF3 and amplification of E2F1." (PMID 26395002, 2015). "The TRAF-2 factor exerts a positive effect on differentiation of B cells, whereas TRAF-3 inhibits the growth and blockade of NF-κB factor in cancer cells." (PMID 25117071, 2014). "While TRAF3 has a well-established role in immune function, mainly via B- and T-lymphocyte regulation, its roles in cancer remain unclear." (PMID 42196397, 2026). "In addition, our data revealed that TRAF3 was more prominently expressed in cancers, such as CHOL, ESCA, HNSC, KICH, KIRC, LIHC, LUSC and STAD." (PMID 38825674, 2024). "Somatic alterations of the TRAF3 gene are also present in other human cancers." (PMID 36776285, 2023). "Some studies have suggested that targeting TRAF3 may be a promising approach for the treatment of certain types of cancer, including HCC." (PMID 37171396, 2023). "Consequently, aberrant function of TRAF3 leads to a broad array of serious diseases in mouse models, including cancers, autoimmune diseases, inflammatory diseases, and infectious diseases." (PMID 36776285, 2023). "TRAF3 has been studied in the context of its potential as a therapeutic target in cancer." (PMID 37171396, 2023). "In cancers, TRAF2 and TRAF3 expressions are different depending on cancer types." (PMID 34257589, 2021). "Loss of TRAF3 may therefore be associated with downregulation of the eRNA-24036 in HPV-associated tumors and could contribute to the spread of cancer." (PMID 34830428, 2021). "Our data indicate that TRAF2 and TRAF3 frameshift mutations and their regional difference as well as altered expressions are present in MSI-H CCs, which could contribute to MSI-H cancer development." (PMID 34257589, 2021). "Indeed, siRNA knockdown of TRAF3 in human cancer cell lines stabilizes NIK and activates NF-κB dependent transcription." (PMID 30692554, 2019). "Similarly, lymphocyte-specific TRAF3 transgenic mice develop autoimmunity, inflammation and cancers (such as squamous cell carcinomas of the tongue, salivary gland tumors, and hepatoma)." (PMID 30294322, 2018).
cancer (continued). "Investigations of normal and transformed epithelial cells of the urinary tract indicate that the activation of cancer cells by mCD40L, but not by sCD40L, leads to the growth and stabilization of TRAF-3 and causes activation of caspase-9 and caspase-3." (PMID 25117071, 2014). "In this sense, the TRAF2 and TRAF3 mutations might inactivate their activities, but their biological functions and contributions to cancer development are not explored in our study and should be further studied." (PMID 34257589, 2021). "The literature suggests that the loss or reduction of Traf3 expression or activation of noncanonical NF-κB signaling might be important for hyperplasia in response to infection or contribute to cancer development." (PMID 33185187, 2020). "The analysis of 33 cancer types revealed that TRAF2, TRAF3, TRAF4, and TRAF7 are predominantly overexpressed, whereas TRAF1, TRAF5, and TRAF6 exhibit lower expression levels." (PMID 38825674, 2024). "This analysis revealed that TRAF1, TRAF2, TRAF3, TRAF4, TRAF6, and TRAF7 exhibit higher expression levels in cancer tissues, whereas TRAF5 is expressed at lower levels in these tissues." (PMID 38825674, 2024). "It was found that depletion of TRAF3 upregulated MHC-I through the NF-κB pathway and TRAF3 small molecule inhibitors increased immuno-sensitivity of cancer cells specifically through MHC-I expression." (PMID 35296095, 2022). "In addition, recurrent breakpoints of SVs targeting cancer genes commonly occurred in frequently deleted regions, e.g., CDKN2A on 9p21.3, MAML2 and ATM on 11q21-22, RAD51B, and TRAF3 on 14q 24-32.3, CYLD and NLRC5 on 16q12.1-13." (PMID 34234122, 2021). "Furthermore, TRAF3 and TRAF6 are crucial for osteoclast differentiation, and therefore can regulate bone metastasis of various cancers." (PMID 30294322, 2018). "This may suggest that CYLD, TRAF3 and NLRC5 aberrations are critical for oncogenesis for a major subset of these cancers." (PMID 29933636, 2018). "The protein levels of TRAF2 and TRAF6 were reduced in cancer cell lines treated with NA, but not TRAF3, TRADD, and FADD." (PMID 25575821, 2015). "Furthermore, TRAF3 and TRAF6 were equivalently expressed in all the cancer cell lines detected." (PMID 37389738, 2023). "Interestingly, also TRAF3 is frequently decreased in human cancers, studies showed that TRAF3 can both positively and negatively regulate tumorigenesis." (PMID 34775479, 2021). "Therefore, the function of USP17 in enhancing inflammation and stemness in cancer cells may result from its ability to bind and disrupt the TRAF2/TRAF3 complex." (PMID 30038267, 2018). "Although RNF216 has several interaction partners, such as TLR4, RIP1, TRAF3 and BECN1, our data showed that only BECN1 was significantly upregulated in CRC cells in response to RNF216 knockdown, supporting that RNF216 contributes to cancer development by regulating autophagy." (PMID 27203674, 2016). "After TNFα, TRAF3 or GADD45A is knockdown in the HCC cells, both mono-treatments and combination treatment failed to induce apoptosis; and the combination treatment failed to exhibit its synergistic effect in inhibiting the cancer growth." (PMID 34025421, 2021). "In our study, we could not separately evaluate the contribution TNFα, TRAF3 and GADD45A in the combination treatment-enhanced apoptosis because knockdown of either TNFα, TRAF3 or GADD45A can completely abolish the treatment-induced apoptosis and the synergy in inhibiting cancer cell growth." (PMID 34025421, 2021).
infection (63 papers, 2009 to 2025). The state of being infected such as from the introduction of a foreign agent such as serum, vaccine, antigenic substance or organism. "Study of Francisella novicida has suggested that E3 ligase HECTD3, which promotes K63-linked polyubiquitination of TRAF3 and thus type I interferon production, is affected by bacterium during infection." (PMID 37841261, 2023). "The TRAF3-linked ubiquitination in the IAV-treated group was obviously increase compared with the non-infection group." (PMID 35573779, 2022). "Mechanistically, MYSM1 translocated to the cytoplasm upon infection to remove K63-linked ubiquitin chains from TRAF3 and TRAF6, terminating type I IFN induction, before being rapidly degraded itself." (PMID 33808506, 2021). "In ISG15 knock-down cells, the RIG-I/MAVS association occurred later at 6 hrs post-infection with an increase in TRAF3 association at 9–12 hrs post infection." (PMID 22022264, 2011). "Further understanding of the effect of T cell TRAF3 deficiency on T cell function in the context of infection could also provide important information about signaling requirements in immune cell interactions, such as Tfh-GC B cell interactions." (PMID 36814922, 2023). "However, the presence of TRAF3 in association with MAVS at 2 hrs post-infection in the control cells correlates with its association with PKR which indicates that the MAVS pathway can be activated through PKR as soon as 2 hrs post infection." (PMID 22022264, 2011). "In conclusion, the TRAF3 gene can negatively regulate the resistance of lung epithelial cells to A. fumigatus, which plays an important role in the early infection processes of A. fumigatus." (PMID 38018974, 2024). "After transferring the infected zebrafish to sterile E2 medium, the fungal load in TRAF3-overexpressing transgenic zebrafish was significantly higher than that in wild-type zebrafish at all time points post-infection as infection time increased." (PMID 38018974, 2024). "Survival analysis showed that the survival rate of TRAF3-overexpressing transgenic zebrafish (31%) after infection was significantly lower than that of wild-type zebrafish (51%)." (PMID 38018974, 2024). "In this study, we demonstrated that the TRAF3 gene plays an important role in the early infection of A. fumigatus by regulating the resistance of lung epithelial cells to A. fumigatus." (PMID 38018974, 2024). "The results of qRT-PCR showed that the expression of TRAF3 was significantly decreased according to the time of infection of zebrafish larvae with A. fumigatus." (PMID 38018974, 2024). "In this study, we investigated the function of TRAF3 in the early stages of infection with A. fumigatus using lung epithelial cells (A549) in vitro." (PMID 38018974, 2024). "The findings above established TRAF3’s importance for robust T cell responses, but its role in individual signals in the complex environment of immunization or infection remained unclear." (PMID 36814922, 2023). "TNF receptor-associated factor 3 (TRAF3) was shown to be recruited in the TCR/CD28 signalling complex in murine CD4+ T cells and critical for T cell-mediated immunity to infection." (PMID 35142878, 2022). "In RPs, inflammation-related genes and signaling pathways, such as the TRAF3 and NF-Kappa B signaling pathways, were upregulated after infection." (PMID 35458449, 2022). "Another infection-related function of USP25 involves the degradation of TRAF3, which induces endotoxin tolerance in macrophages." (PMID 34249948, 2021). "Upon infection with an RNA or DNA virus, USP25 associates with TRAF3 and TRAF6 and protects TRAF3 and TRAF6 from virus-induced proteasome-dependent or independent degradation." (PMID 34249948, 2021). "Previous studies showed that infection of HEK293T cells with SeV enhanced the interaction of TRAF3 with both its upstream regulator MAVS and downstream effector TBK1." (PMID 33411856, 2021).
infection (continued). "In response to H1N1 or H3N2 infection, on day 5 post infection there were also similar expression patterns of Mavs, Traf3, and Traf6 detected in young lung." (PMID 34829979, 2021). "Transfection of NS1 but not NS2 into A549 cells reduced the protein levels of TRAF3 in the cells, while infection with ΔNS1-RSV increased the levels of TRAF3 compared to WT RSV infection." (PMID 32290326, 2020). "Binding analysis revealed that both PINK1 wild type (WT) and PINK1 L347P interacted with TRAF3 in HEK293T cells in a VSV-infection independent manner, whereas the kinase domain-deleted PINK1ΔKD mutant did not." (PMID 31139191, 2019). "When enough miR-576-3p accumulates in cytoplasm (6 h post-infection) the target mRNA levels, mainly for TRAF3 and STING, begin to fall progressively)." (PMID 29813068, 2018). "Our analysis also showed that activators genes involved in innate immune response through IFN-β pathway, as STING (Stimulator of Interferon Genes) and TRAF3 (TNF-Receptor Associated Factor 3), were down-regulated as the infection progress." (PMID 29813068, 2018). "After palmitate administration, Adca-TAK1 markedly blunted insulin signalling in both TRAF3-flox and TRAF3-LKO cells, whereas the TRAF3 overexpression-induced impairment of insulin signalling was largely reversed by Addn-TAK1 infection in primary hepatocytes." (PMID 26882989, 2016). "The expression of type I IFN elicited by the infection of RNA viruses was severely reduced in TRAF3-deficient mouse embryonic fibroblast (MEF) cells, indicating a crucial role for TRAF3 in RLR-dependent signaling." (PMID 24788966, 2014). "The TNF receptor-associated factor 3 (TRAF3), a cytoplasmic adaptor protein and an important component of toll-like receptor (TLR) signaling, inhibits chronic inflammation and pathogenic infection in macrophages." (PMID 39967660, 2025). "Therefore, experiments were designed for the overexpression of the TRAF3 gene in vivo and in vitro models to, in turn, demonstrate the function played by the TRAF3 gene during the early infection of A. fumigatus." (PMID 38018974, 2024). "To assess whether TRAF3 plays a role in lung epithelial cell interactions with macrophages after infection with A. fumigatus, we constructed an in vitro A. fumigatus spore-A549-macrophage co-culture model." (PMID 38018974, 2024). "TRAF3 upregulation showed significant differences after 36 h of BIV infection (p < 0.001)." (PMID 36552207, 2022). "Furthermore, the activity of influenza virus mini-replicon vRNPs was also significantly inhibited in TRAF3 overexpression cells, suggesting that TRAF3 was downregulated upon infection with influenza virus by affecting the activity of vRNPs." (PMID 35573779, 2022). "Interestingly, TRAF3 inhibits H. pylori infection-induced NF-κB activation and Cdx2 expression, and is required to resist the infection by acting in the NOD1-RIP2-TRAF3 pathway in gastric epithelial cells." (PMID 30294322, 2018). "And TRAF3 mRNA levels were slightly upregulated after 6 hr infection with SeV." (PMID 29734366, 2018). "Thus, our results indicated that knockdown of TRAF3 in A549 cells may promote the intracellular infection of influenza virus." (PMID 35573779, 2022). "TRIM33 modulates the functions of TRAF3 and NEMO, augmenting or suppressing macrophage inflammatory responses depending on the infection status." (PMID 39981097, 2025). "The transcript and protein levels of IFN-α, IFN-β, RIG-I, MDA5, MAVS, TRAF3, TBK1, and IRF3 in the PRRSV-ICs-infected cell group were significantly diminished at 12 h and 24 h post-infection compared to those in the PRRSV-PNI-infected cell group." (PMID 41012704, 2025). "Our findings highlighted distinct differences between the infection groups of CT-P10 and CT-P120 PEDV strains, specifically in the expression levels of proteins such as TRAF3, IRF3, NFKB1, and ISG15." (PMID 37515115, 2023).
infection (continued). "Significantly, our results showed that the expression of six major adaptor molecules (Myd88, IRAK2, IRAK4, TRAF3, TBK-1 and IRF7) downstream of RNA sensors were dramatically decreased in the PAMs with a PRRSV-ADE infection." (PMID 36680075, 2022). "These signaling pathways showed that, after LPS infection, several DEGs were mainly related to immune function, such as up-regulated expression of CCL5, IL8, NFKBIA, TRAF3, and TNFAIP3, and down-regulated expression of MEF2C, MAP2K6, TLR1, TLR2, and IRF5." (PMID 34067819, 2021). "ii) TLR3, a receptor for viral dsRNA, displayed a strong reduction in influenza virus and icMERS infection, while TICAM1, TRAF1, TRAF2, TRAF3 and TRAF6, adaptors responsible for TLR3, changed in an opposite direction with TLR3." (PMID 34248940, 2021). "In that study, Vpr promoted infection in macrophages and dendritic cells, despite HIV induced formation of innate immune signaling complexes containing TBK1, IRF3, and TRAF3, visualized by immunofluorescence staining." (PMID 33300875, 2020). "The expression levels of zbTRIM25 and its downstream genes, RIG-I, MAVS, TRAF3, IRF3, and IFN 1 decreased to some different extent at 24 h post RGNNV infection in miR-202-5p mimics transfected ZBE3 cells." (PMID 32120903, 2020). "We noticed that some studies have shown that protein levels of MAVS, or TRAF3, or TRAF6 were downregulated to some extent after infection with different viruses." (PMID 29734366, 2018). "In the late termination stage of infection, LUBAC mediates the linear ubiquitination of NEMO that facilitates its interaction with TRAF3 and disrupts the MAVS-TRAF3 complex." (PMID 29599773, 2018). "At 12 h post-infection, as result of the decrease of STING and TRAF3 mRNA levels, the IFN-β response begins to be relieved, starting a feedback mechanism that leads to a halt in antiviral response and sustaining viral replication." (PMID 29813068, 2018). "As STING, MAVS and TRAF3 were demonstrated to be key factors in regulation of that response, we aimed to quantify the variation in IFN-β transcripts in response to the infection." (PMID 29813068, 2018). "Of note, the expression of both TRAF3 and TRAF6 were unaffected by the infection (expressed below the threshold of detection)." (PMID 28993767, 2017). "Phosphorylation of IRF3 triggered by SeV-infection was greatly inhibited and the production of IFN-β was blocked when TRAF3 or TRAF6 was deleted." (PMID 26456228, 2015). "MAVS was immunoprecipitated from the cell extracts at different times post-infection and the presence of PKR and RIG-I was examined in the immunocomplexes, as well as that of TRAF3, used as marker of activation of the MAVS signaling pathway." (PMID 22022264, 2011). "In contrast to that observed in TRAF3−/− MEF, levels of mRNA and secreted IFN-β in TRAF6−/− cells supernatants were equivalent to wild type cells at 24 hours post infection (P>0.2) but slightly reduced at 48 hours (∼2-fold decrease, P<0.0001)." (PMID 19798431, 2009). "The transcript and protein levels of IFN-α, IFN-β, RIG-I, MDA5, MAVS, and TRAF3 in the PRRSV-infected cell group and poly (I: C)-stimulated cell group were significantly elevated at 12 h and 24 h post-infection compared to those in the mock-infected cell group." (PMID 41012704, 2025). "The transcript and protein levels of IFN-α, IFN-β, RIG-I, MDA5, MAVS, TRAF3, TBK1, and IRF3 in the PRRSV-infected cell group by anti-FcγRI IgG pre-treatment were significantly declined at 12 h and 24 h post-infection compared to those in the PRRSV-infected cell group by RNI pre-treatment." (PMID 41012704, 2025). "Moreover, AF-9 strain infection or poly (I: C) stimulation led to upregulation of the production of RIG-I, MDA5, MAVS, TRAF3, and TBK1 and phosphorylation of TBK1 and IRF3 in PAMs." (PMID 41012704, 2025).